IL6 (interleukin 6)
Diseases named in the same sentence as IL6 in open-access papers (continued):
Sharing a sentence is not in itself a finding about the gene and the disease.
Sepsis (continued). "In patients with sepsis complicated with ARDS, sivelestat sodium treatment significantly improved the inflammatory indicators (IL-6, PCT, CRP) and the oxygenation index (PaO2/FiO2), and significantly reduced the duration of mechanical ventilation time and ICU stay, and the incidence of VAP." (PMID 40842872, 2025). "Our results could help fill the gap in the current understanding of IL-6 and leukocyte CPD application in the early course of sepsis in both immunocompetent and immunocompromised patients." (PMID 40142279, 2025). "Interleukin-6 (IL-6), a key mediator of systemic inflammation, has been proposed as a prognostic biomarker in sepsis, but its predictive value in melioidosis has not been systematically evaluated." (PMID 41439926, 2025). "Therefore, the clinical application values of IL-6, IL-8, and SAA in the treatment of sepsis in premature infants need further exploration." (PMID 39886481, 2025). "We plan to validate the efficacy of these drugs in sepsis mouse models, such as those induced by intraperitoneal injection of LPS or cecal ligation and puncture (CLP), observing their impact on inflammatory cytokines (e.g., TNF-α and IL-6) and survival rates." (PMID 40124361, 2025). "In infants with NEC, this difference in IL-6 values between gram-negative and gram-positive blood sepsis was not statistically significant (2204 vs 330 pg/mL, P = .297)." (PMID 39958363, 2025). "Moreover, our results also provide evidence that sivelestat sodium can significantly improve inflammatory indicators (including IL-6, PCT, CRP) and oxygenation function (PaO2/FiO2 ratio) in patients with sepsis complicated with ARDS." (PMID 40842872, 2025). "LPS-induced sepsis triggers a systemic cytokine storm marked by sharp increases in pro-inflammatory mediators, particularly interleukin-6 (IL-6) and tumor necrosis factor-alpha (TNF-α), both of which play central roles in sepsis pathogenesis and organ dysfunction." (PMID 40871061, 2025). "LCA further resolved this phenotype into two subtypes: an “IL-6 moderate” group with sepsis but no neutropenia (class 2), and an “IL-6 high” group with both sepsis and neutropenia (class 4)." (PMID 41155261, 2025). "Although they produce IL-6 in response to inflammatory factors, they have not been comprehensively investigated in mice or humans under conditions of sepsis." (PMID 39568061, 2025). "Gene expression of cytokines IL-1β (Il1b) and IL-6 (Il6), but not Tnf (Tnf) was upregulated in acute and prolonged sepsis." (PMID 39821755, 2025). "Regarding IL-6 clearance, the overall pooled AUROC is 0.828 (95% CI: 0.736–0.919), indicating that IL-6 levels within the first 96 h have good discriminatory power for predicting mortality in sepsis patients." (PMID 40149943, 2025). "IL-6 induced muscle atrophy of mice and acute lung injury (ALI) in sepsis through JAK-STAT signaling pathway, and IL-6 was the favorable target for sepsis inflammation." (PMID 39891057, 2025). "In sepsis patients, the increased TNF-α and IL-6 levels indicate severe inflammatory response." (PMID 41393152, 2025). "IL-6, in conjunction with other biomarkers such as C-reactive protein (CRP) and procalcitonin, may improve the accuracy of sepsis diagnosis and help guide antibiotic therapy." (PMID 40242671, 2025). "An animal study reported reduced serum interleukin-6 (IL-6), high mobility group protein B1 (HMGB)-1, and tumor necrosis factor-α(TNF-α) levels but increased interleukin-10 (IL-10) levels in the group given esmolol compared with the sepsis group." (PMID 40522976, 2025). "To more rigorously evaluate the independent effect of DAPA, we performed multivariate Cox regression analysis, adjusting for potential confounding factors such as sepsis severity (measured by APACHE II and SOFA scores), inflammatory biomarkers (e.g., IL-6), and other relevant clinical variables." (PMID 40001588, 2025).
Sepsis (continued). "In survivor vs. non-survivor trajectories, non-survivors exhibited persistent elevations of IL-6, IL-8, G-CSF, and MCP-1 (up to 10,000-fold differences) associated with sepsis and multi-organ failure." (PMID 41155423, 2025). "In this study, serum levels of IGFBP-3, C-reactive protein, procalcitonin, lactate, interleukin-6, and mid-regional pro-adrenomedullin were measured upon admission to the internal medicine unit (IMU) in 139 patients with microbiologically confirmed sepsis." (PMID 40724799, 2025). "This study aims to evaluate the prognostic utility of admission levels of PT-INR, IL-6, and HDL cholesterol in severe sepsis patients, correlating these biomarkers with clinical severity and outcomes to improve early prognostication and treatment strategies in resource-limited ICU settings." (PMID 40959673, 2025). "Administering these pro-DCD-specific IgGs significantly increased sepsis-induced systemic accumulation of granulocyte colony stimulating factor (G-CSF), interleukin 6 (IL-6), and monocyte chemoattractant protein 1 (MCP-1)—three established surrogate markers of experimental and clinical sepsis." (PMID 40806779, 2025). "Fli-1 in pericytes may serve as a crucial mediator of neuroinflammation during sepsis by directly regulating pivotal cytokines such as MCP-1 and IL-6." (PMID 39862276, 2025). "Large series further show that mortality is markedly higher in patients who develop pneumonia or sepsis, and that prolonged FN-related hospital stays are frequently accompanied by low MASCC scores, thrombocytopenia, and elevated procalcitonin, IL-6, and D-dimer levels." (PMID 41590334, 2025). "In addition, cytokines such as IL-6 and TNF-α as well as markers of endothelial dysfunction have important prognostic value in the immunopathological process of sepsis." (PMID 41315982, 2025). "However, ACE also drives pro-inflammatory signaling via Ang II–AT1R activation, inducing cytokine release (TNF-α, IL-6, IFN-γ) and ROS production, potentially exacerbating inflammation in sepsis or viral infections." (PMID 40722848, 2025). "The PPV (84.6%) and NPV (81.8%) further suggest that IL-6 is reliable in predicting both positive and negative cases of sepsis." (PMID 40242671, 2025). "In sepsis, a large number of proinflammatory cytokines (TNF- α, IL-6, IL-1 β) are released, triggering a cascade of inflammatory responses, leading to cardiomyocyte damage, mitochondrial collapse, deregulation of calcium homeostasis and, ultimately,myocardial contractile dysfunction." (PMID 40276499, 2025). "Many of the immunological markers discussed in this review, such as interleukin-6 (IL-6), tumor necrosis factor-alpha (TNF-α), interleukin-1 beta (IL-1β), and myeloperoxidase (MPO), have been extensively studied in the contexts of sepsis, cardiovascular disease, or general critical illness." (PMID 40710793, 2025). "Panax ginseng and its active ginsenosides (e.g., Rg1) have been shown to alleviate intestinal barrier disruption and suppress pro-inflammatory cytokines in CLP-induced sepsis, potentially through inhibition of the TLR4/NF-κB pathway, leading to reduced IL-6 and TNF-α levels." (PMID 41357500, 2025). "The mechanism of action of LSECs in sepsis is complex and diverse, involving multiple aspects such as the TLR4 signaling pathway, PD-L1-mediated immune regulation, the secretion of cytokines like IL-6 and CXCL10, and the regulation of Tregs." (PMID 40072101, 2025). "We also measured the concentrations of IL-6 and LCN2, establishing serum markers of sepsis." (PMID 40230851, 2025). "The hyperactivation of the immune system during sepsis leads to a cytokine storm, characterized by the excessive release of pro-inflammatory cytokines, including tumor necrosis factor-alpha (TNF-α), interleukin-1 beta (IL-1β), and interleukin-6 (IL-6)." (PMID 39803908, 2025).
Sepsis (continued). "Indeed, pegylated pro-DCD-C34S significantly attenuated sepsis-induced accumulation of G-CSF, IL-6, KC/GRO-α, MCP-1, MIP-2/GRO-β, and sTNFRI, six surrogate markers of experimental sepsis." (PMID 40534887, 2025). "While standard clinical parameters and inflammatory markers such as CRP, PCT, and IL-6 were elevated in both groups, they lacked the specificity to distinguish sepsis origin." (PMID 40510342, 2025). "In addition, several markers, including Calprotectin, Azurocidin, IL-6, IL-8, IL-10, TNF-α, and IL-35, were progressively elevated from SIRS to Sepsis_A and Sepsis_D cohorts, reflecting disease severity." (PMID 41301767, 2025). "The results demonstrate that IL-18, IL-6, MCP-1, and IL-10 are increased in sepsis, while IL-18 may serve as an additional biomarker for distinguishing abdominal from non-abdominal sepsis." (PMID 40510342, 2025). "From a translational standpoint, IL-6 inhibitors such as tocilizumab may therefore have therapeutic relevance in limiting aberrant fibrinogen and TPO upregulation in sepsis and other thromboinflammatory conditions." (PMID 41157266, 2025). "Interleukin (IL)-6, a standard marker in many ICUs, correlates with an poor outcomes in sepsis but does not differentiate infection sources." (PMID 40510342, 2025). "Our results indicated that acute abdomen III could lower blood concentrations of IL-6, IL-1β, and TNF-α in the sepsis model, consistent with previous findings." (PMID 40582762, 2025). "Our finding that IL-6 is elevated irrespective of the infection focus in clinically apparent sepsis consolidates this knowledge." (PMID 40178612, 2025). "The presence of interleukin (IL)‐2, IL‐4, IL‐5, IL‐6, IL‐8, IL‐10, TNF‐α and interferon‐γ was significantly more evident in all three cell culture media transfected with plasma from sepsis patients than in controls, indicating that the transfected cells potentially underwent necroptosis." (PMID 40318009, 2025). "Similarly, under the influence of sepsis-induced inflammation, senescent cells release SASP factors such as IL-6 and TNF-α." (PMID 40299574, 2025). "Lung injury, unlike IL-6, was at low levels in the early period of sepsis, peaked at the 8th hour, and continued at the same level until the end of the 24th hour." (PMID 39955435, 2025). "In this study, we revealed that T0 protects against sepsis-related ALI via the following mechanisms: the total protein in the BALF was decreased; TNFα and IL6 mRNA expression levels were decreased in animals and cells; H&E staining revealed that the degree of lung injury was improved." (PMID 40994643, 2025). "According to a prospective cohort study, early measurement of serum IL-6 levels can indicate disease severity in sepsis, regardless of immune status." (PMID 40823032, 2025). "Si-CSN6 reduced IL-1β, IL-6, and TNF-α levels in an in vitro sepsis model (n = n= 6 per group)." (PMID 40595050, 2025). "Additionally, sepsis patients had markedly increased median levels of CRP, PCT, and IL-6 compared to healthy controls." (PMID 40568710, 2025). "During the hyperinflammatory phase of sepsis, macrophages play a crucial role in monitoring the infection through their ability to phagocytose bacteria, present antigens, and produce significant amounts of cytokines such as TNF-α, IL-6, and IL-1β." (PMID 38799158, 2024). "Additionally, our findings demonstrated that LBT effectively downregulated the levels of IL-6, TNF-α, and IL-1β in serum samples while inhibiting inflammatory cell infiltration within lung and liver tissues induced by LPS-induced sepsis." (PMID 38799158, 2024). "Moreover, when evaluated in vivo on mice sepsis model, both nanosystems have demonstrated a superior effect over the uncoated AMPNP regarding the reduction in serum cytokines (IL-1β, TNF-α, and IL-6) levels and inflammatory cells tissue infiltration." (PMID 38637839, 2024).
Sepsis (continued). "Contradictory results have emerged, such as the finding that high doses of recombinant IL-6 did not elicit adverse effects in healthy dogs, indicating that IL-6 plays a complex role in sepsis." (PMID 39056754, 2024). "IL-6 has already been demonstrated to be a strong predictor of severity in sepsis and with Gram-negative bacterial sepsis." (PMID 38672079, 2024). "We observed an isolated elevation of IL-6, an early marker of inflammation, without significant changes in other cytokines usually seen in context of sepsis or bacterial infections." (PMID 39076993, 2024). "The current diagnosis of sepsis relies on clinical evaluation, blood or urine cultures, and detection of inflammatory response biomarkers such as C-reactive protein (CRP), procalcitonin (PCT), and interleukin 6 (IL-6)." (PMID 38637839, 2024). "Kuster and colleagues also took the approach of measuring cytokines at baseline and at the time of suspected sepsis in VLBW infants and found IL-1ra and IL-6 to have high sensitivity and specificity in 21 cases of late-onset sepsis, even measured from samples taken the day prior to blood culture." (PMID 38312920, 2024). "Interleukin-6 (IL-6) is useful as a TBI marker, particularly in cases of sepsis." (PMID 39595464, 2024). "Sepsis is a severe clinical syndrome due to the host response to infection, exacerbated by the production of both pro-inflammatory cytokines (TNF-alpha, IL-1-beta>alpha, IL-6, il-8, IL-12, IL-17, COX-2, IRF3) and anti-inflammatory (IL-10) cytokines." (PMID 39768405, 2024). "As a result of the judicious selection of electrode design, it is possible to detect sepsis biomarkers with unprecedented sensitivity, reaching LODs of 0.82 ag mL−1 for PCT, 0.167 ng mL−1 for CRP, 0.202 pg mL−1 for TNF-α, and 0.056 fg mL−1 for IL-6." (PMID 38920613, 2024). "During this pathophysiological process, inflammatory factors such as IL6, TNF-a, and neutrophils may trigger an “inflammatory factor storm,” leading to sepsis-related sequential organ failure." (PMID 38765257, 2024). "Nevertheless, the results of our study here revealed no significance of serum IL-6 levels in evaluating the prognosis of patients with sepsis-induced ARDS." (PMID 39686985, 2024). "The results revealed that IL-6 (OR 1.00, 95% CI 1.00–1.00, p = 0.035), LAC (OR 1.38, 95% CI 1.07–1.89, p = 0.023), and TAPSE/PASP (OR 0.92, 95% CI 0.88–0.96, p = 0.002) were found to be independent prognostic factors for sepsis patients." (PMID 38961249, 2024). "One (6%) study also showed increased IL-6 levels in obese septic mice compared to non-obese non-septic mice at 12-, 14- and 48-h post-sepsis." (PMID 38388878, 2024). "Overall, GM-CSF and IL-6-induced PMN-MDSCs have similar phenotypes and functions to sepsis-derived PMN-MDSCs, which may be suitable for this study." (PMID 38385073, 2024). "The three major pro-inflammatory cytokines TNF-α, IL-1β and IL-6 were not specific for sepsis and their primary role as biomarkers of sepsis appears to be prognostic rather than diagnostic." (PMID 38643461, 2024). "The correlation of T lymphocyte subgroup, IL-6, and PCT with sepsis severity was examined." (PMID 39465765, 2024). "In sepsis patients, anti-inflammatory reactions are recognized with the pro-inflammatory response (The increase of IL-10 correlated with the rise of TNF-alpha, IL-6, and IL-8.)." (PMID 38375470, 2024). "Sepsis is characterized by two distinct phases: an initial hyper-inflammatory phase characterized by a remarkable surge in potent cytokines like TNF-α and IL-6, followed by an immunosuppression phase wherein inflammatory cytokines levels significantly decrease." (PMID 38348451, 2024). "Notably, in the early phases of sepsis, Kupffer cells increase the activation of many pro-inflammatory regulators such as MCP-1, MIP-2, IL-6, IFN-γ, and TNF-α." (PMID 39769181, 2024).
Sepsis (continued). "Moreover, we found that serum levels of IL-6 and TNF-α were significantly higher in patients with septic shock compared to those with sepsis (Fig. EV4H), suggesting that IL-6 and TNF-α are closely associated with the progression of sepsis." (PMID 39294473, 2024). "As expected, levels of IL-6 and TNF-α in the plasma were increased in the setting of sepsis." (PMID 38957471, 2024). "Plasma levels of the proinflammatory cytokine IL-6 and the neutrophil chemokine, IL-8, were also significantly elevated in the sepsis patients (P<0.02), but the elevations were not significantly different between the patient groups." (PMID 38524125, 2024). "Sepsis diagnosis is based on the presence of certain biomarkers in the patient’s blood, for instance, C-reactive protein (CRP), procalcitonin (PCT), tumor necrosis factor-alpha (TNF-α), high-mobility group box 1 protein (HMGB-1), and interleukin-6 (IL-6)." (PMID 38920613, 2024). "IL-6 and S100A8/A9 are closely related to S. aureus septic arthritis and sepsis in mouse models." (PMID 39204252, 2024). "The underlying mechanism of this toxicity is unclear, and some studies suggested that an inflammation pathway including the IL‐6, iNOS, TNF‐α, and CD64 was involved, and a set of genes and proteins were found to play a role in neutrophil granulopoiesis in sepsis." (PMID 39305165, 2024). "The TNF signaling pathway has a critical role in modulating immune cell responses as it can elicit a multitude of effects, including fever, apoptosis, cachexia, inflammation, suppressed tumor growth and viral replication, and sepsis responses through induction of IL1 and IL6." (PMID 39051372, 2024). "The cecal gene expression of IL-6, IL-1β, TNF-α, IL-17A, IL-22, and CRAMP (homologue of human cathelicidin LL-37) was significantly elevated in mice with gut-derived P. aeruginosa sepsis." (PMID 38790988, 2024). "Furthermore, the specific deficiency of TREM2 in macrophages decreased the production of IL-6, IL-1β, and TNF-α in the lung of sepsis mice." (PMID 39405126, 2024). "Similarly, numerous reports note elevation in serum concentrations of IL-1β, IL-6, IL-8, and TNF-α between neonatal individuals with sepsis and the corresponding control cohorts." (PMID 38510969, 2024). "Testing all 127 possible cytokine combinations for ruling out sepsis revealed that adding any other cytokine to IL-6 did not result in a higher PPV." (PMID 38671704, 2024). "During sepsis, the presence of LPS can trigger the TLR4 signaling pathway, leading to the translocation of NF-κB, subsequently impacting the expression of pro-inflammatory cytokines, such as IL-1β and interleukin-6 (IL-6)." (PMID 39677961, 2024). "Furthermore, the baseline excessive pro-inflammatory cytokines, such as TNF-α, IL-6, IL-1α, IL-1β, and IL-18, released after hepatic cell damage in NASH or further stage, might predispose NAFLD patients to cytokine storm in the setting of sepsis, resulting in worse outcomes." (PMID 39407795, 2024). "Through five cases of sepsis patients, we showed that the number of bacteria is a novel useful biomarker that more sensitively reflects the therapeutic effect than currently available biomarkers (BT, WBC, CRP, presepsin, and IL-6)." (PMID 38216600, 2024). "Other common sepsis markers are CRP, procalcitonin, and interleukin-6 (IL-6)." (PMID 39091978, 2024). "Another study investigated the role of FGD5-AS1 in sepsis and LPS-induced inflammation and showed that FGD5-AS1 overexpression increased AQP1 and decreased miR-133a-3p expression, subsequently reducing inflammatory cytokines such as TNF-α, IL-6 and IL-1β." (PMID 39544938, 2024). "Plasma from sepsis patients who developed ARDS further increased IL‐6 and sICAM‐1 compared to plasma from sepsis patients without ARDS and healthy plasma." (PMID 38981846, 2024).